ALK (ALK receptor tyrosine kinase)
Diseases named in the same sentence as ALK in open-access papers (continued):
Sharing a sentence is not in itself a finding about the gene and the disease.
tumor (continued). "ALK IHC-positivity was significantly associated with a shorter disease-free survival, tumor-specific survival, and overall survival (P = 0.001, 0.026, and 0.007, respectively)." (PMID 29156778, 2017). "In 2008 ALK emerged also as a major predisposition gene in NB, paving the way for new target-based therapeutical approaches for this tumor." (PMID 28915608, 2017). "During tumor progression of fragile patients, this non-invasive approach can investigate persistent rearrangement or detect resistance mutation onset in the ALK gene and thereby treatment can be adapted with respect to the observed mutation." (PMID 28805673, 2017). "At the time of disease progression, an ALK resistance mutation was detected in both a new tumor biopsy (L1196M) by whole exome sequencing and in CTCs isolated at the same time using Sanger sequencing." (PMID 29312651, 2017). "Anaplastic lymphoma kinase (ALK) is a receptor tyrosine kinase that has been implicated in the pathogenesis of a variety of neoplasms." (PMID 28895885, 2017). "Of these, four KRAS mutations, two NRAS mutations, two histone H3 mutations, and one ALK mutation were predicted to encode epitopes in at least one tumor." (PMID 28854978, 2017). "In the last two decades, new genetic and cytogenetic mutations in the tyrosine kinase, anaplastic lymphoma kinase (ALK), have been implicated in the pathogenesis of several neoplasms." (PMID 28895885, 2017). "Some studies have also raised diagnostic criteria including: 1) round-to-epithelioid tumor cells; 2) abundant myxoid stroma with inflammatory infiltrate; 3) immunopositivity for ALK." (PMID 28535796, 2017). "In the EGFR and ALK mutations, targeted therapy inhibits the growth of tumor cells by blocking the activity of tyrosine kinase." (PMID 28327204, 2017). "In patients carrying a mutation in the anaplastic lymphoma kinase (ALK) gene in their primary tumor, single-cell WGA and sequencing detected the same mutation in single DTCs from bone marrow." (PMID 28405930, 2017). "FISH analysis of tumor specimens for diagnostic testing of biomarkers such as ALK- or ROS1-rearrangement is in most cases still done manually by cytogeneticists." (PMID 27417942, 2016). "The cell line, in vitro kinase and Ba/F3 cell assays presented here are strongly consistent with rapid and robust abrogation of tumor growth in both human implanted and murine endogenous tumors driven by highly resistant ALK mutations." (PMID 27483357, 2016). "Analysis of the ALK mutations in the pre-treatment tumor samples of patients #1 and #3 by Sanger DNA sequencing revealed no mutations." (PMID 27045755, 2016). "FISH analysis of the chromosome 2 centromere in all cases classified by FISH as ‘ALK gene copy number gain’ showed that ALK gene copy number gain in RMS tumor cells was associated with polysomy of chromosome 2." (PMID 27385213, 2016). "To exclude presence of a minor clone with the ALK mutation in the pre-treatment tumor samples we performed ddPCR." (PMID 27045755, 2016). "Ectopic expression of L1196M and C1156Y leads to resistance to crizotinib in EML4-ALK-transformed Ba/F3 cells, indicating that these tumor-derived L1196M and C1156Y mutations decrease the tumor's sensitivity to ALK inhibitors." (PMID 26802023, 2016).
tumor (continued). "Different types of alterations in the ALK gene have been implicated in human cancer tumorigenesis, and different tumor types have different structural alterations in the ALK gene." (PMID 26966027, 2016). "The profile of ALK TKI resistance mutations likely to arise in a tumor, therefore, is inherently shaped by ALK's fusion partner, as should choices of alternative therapy." (PMID 27009859, 2016). "In this study, we assessed the feasibility and performance of applying targeted deep sequencing to plasma cfDNA to detect and quantify ALK rearrangements as well as other somatic mutations to survey tumor dynamics." (PMID 27564104, 2016). "The detection of ALK mutations in post-treatment tumor samples of two patients underlines their role in crizotinib resistance." (PMID 27045755, 2016). "Surprisingly, FISH analysis revealed an ALK structural rearrangement coupled to copy number gain in the 100% of the analyzed tumor cells, suggesting the existence of an ALK truncated variant in this patient." (PMID 27385213, 2016). "In the ALK-positive group, three out of 14 tumor tissues exhibited morphology that is associated with ALK rearrangements." (PMID 26993609, 2016). "ALK kinase domain mutational status was investigated in ALCL tumour specimens by 454 amplicon ultra-deep sequencing." (PMID 25874976, 2015). "Ganetepib, which is an Hsp90 inhibitor, has been shown to be effective in patients with secondary ALK mutations and in tumor cells with ALK amplification." (PMID 25888090, 2015). "These mainly occur through ALK tyrosine kinase domain punctual mutations, ALK gene amplification and/or activation of compensatory signaling pathways and more than one mechanism can develop simultaneously within the same tumor." (PMID 26338968, 2015). "ALK rearrangement is a potential actionable driver mutation in CRC based on survival inhibition of patient tumor-derived cell line by potent ALK inhibitors." (PMID 26172300, 2015). "ALK (anaplastic lymphoma kinase) is an oncogenic receptor tyrosine kinase associated with many tumor types." (PMID 25950466, 2015). "Overall, a total of 17 patients showed one or two ALK mutations after analysis of DNA tumor samples by ddPCR." (PMID 25653133, 2015). "We and others have recently shown that anaplastic lymphoma kinase (ALK) is another transmembrane receptor that identifies high-risk tumours independently of PAX3-FOXO1 expression and RMS histology." (PMID 26147305, 2015). "Tumours with ALK fusion mutations are responsive to the tyrosine kinase inhibitor crizotinib however, as with EGFR mutations and TKIs, resistance develops with evidence of secondary ALK point mutations and activation of EGFR signalling in some cases." (PMID 26101870, 2015). "Intra-tumor heterogeneity caused by crizotinib resistance results from the L1196M gatekeeper ALK mutation, and other ALK secondary C1156Y mutations co-existed in malignant pleural effusion of a patient who acquired crizotinib resistance." (PMID 24952482, 2014). "Overall, we suggest that the anticancer effect of Crizotinib is associated with the inhibition of ALK signaling pathway, which finally leads to the inhibition of tumor growth and induction of apoptosis in PANC-1 xenograft models." (PMID 25193856, 2014). "In this study, we investigated the ability of ALK-wt, and the most common activating mutations, ALK-F1174L and ALK-R1275Q, to initiate tumor formation in NCPC, and we compared their in vivo oncogenic potential." (PMID 24947326, 2014).
tumor (continued). "Tumor cells expressing ALK mutations depend on this oncogene for their survival and are typically sensitive to ALK inhibitors such as TAE684." (PMID 25228590, 2014). "ERBB3 show several similarities to ALK, encoding the NB familial gene, and thus made a good candidate gene with potential role in the tumour development of r4 tumour types." (PMID 23835063, 2013). "No other genetic event characteristic for NBs, including other segmental chromosomal aberration(s), LOHs or an ALK gene point mutation was found in the tumor." (PMID 24131700, 2013). "Since this ALK mutation was inherited from asymptomatic parents, additional genetic events are thought to be required for tumor development in these patients." (PMID 24205241, 2013). "The ALK (chromosome band 2p23) gene has been implicated in the pathogenesis of IMT supporting neoplastic origin of tumor." (PMID 23691372, 2013). "Novel therapies targeting overexpressed proteins associated with tumor progression, such as ALK, PI3K, mTOR, Aurora, and tyrosine kinases are promising." (PMID 24396620, 2013). "The Phase I protocol was amended to include patients with ALK-positive tumors, and within a few months of enrolling the first patients with the ALK mutation, objective tumor responses were seen in ALK-positive NSCLC patients." (PMID 23369459, 2012). "The tumor cells harboring either C1156Y or L1196M mutations had a very low response to ALK inhibitors." (PMID 23109866, 2012). "Each mutation developed independently in subclones of the tumor and conferred marked resistance to two different ALK inhibitors, PF-02341066 and a 2,4-pyrimidinediamine derivative (PDD)." (PMID 22192458, 2011). "ALK was recently recognized as the NB predisposition gene and has thereafter also been found to be affected in sporadic tumours, either though mutations of the tyrosine kinase domain or by genomic amplification." (PMID 21492432, 2011). "c.1810T allele has been detected in 8.7% of sporadic tumours, which is a similar frequency to the mutations observed for the two known familial NB susceptibility genes (ALK = 12.4%, PHOX2b = 4.3%)." (PMID 20003389, 2009). "After the progression, the molecular testing revealed CCDC6-RET fusion in a liver metastasis, two novel RET fusions (IL6ST-RET and SLC41A3-RET), and an ALK fusion with a mutation allele frequency of 0.19% in circulating tumor DNA (ctDNA), including the known EGFR 19del." (PMID 41907614, 2026). "With the identification of various mutations in tumor tissue by next-generation sequencing, patients with cancer increasingly have access to targeted therapies, including those directed at anaplastic lymphoma kinase (ALK) mutations." (PMID 41948498, 2026). "The switch in immunophenotype and the hyperactivated oncogenic signaling including the PDGFRB-STAT5-IL10 oncogenic axis might suggest epigenetic reprogramming of ALK+ tumor cells upon loss of HDAC1." (PMID 40175628, 2025). "In accordance with the clinical recommendations of the Russian Association of Oncologists (AOR), taking into account the molecular profile of the tumor (ALK mutation), targeted therapy with the drug Alecensa (alectinib, F. Hoffmann-La Roche Ltd., Basel, Switzerland) was started." (PMID 40283345, 2025). "ALK is a critical therapeutic target, as its alterations (mutations, amplifications, and rearrangements) drive tumor development by activating oncogenic pathways, including MAPK/ERK, JAK-STAT, PI3K-Akt, and PLCγ, promoting tumor cell proliferation, survival, and progression." (PMID 40576713, 2025). "Whether adjuvant therapy is required after surgery depends on the surgical margin, ALK gene mutation status, tumor size and location, patient age, and tumor stage." (PMID 40260197, 2025).
tumor (continued). "However, chromosomal rearrangements, especially translocations, cause expression of pathogenic ALK fusion proteins that drive tumor formation and maintenance." (PMID 41469691, 2025). "Genetic testing of tumor tissue revealed a mutation in the ALK gene." (PMID 40283345, 2025). "In this sense, we believe that the functional assay DBP could benefit patients by predicting the cytotoxicity of different ALK inhibitors in living tumor cells, complementing the readout of standard diagnostic assays." (PMID 40113795, 2025). "Similarly, resistance to ALK inhibitors like crizotinib often arises due to mutations in the ALK gene or activation of bypass signaling pathways that sustain tumor growth despite the therapy." (PMID 39941694, 2025). "However, functional studies are needed to elucidate the biological effects of this mutation, including its impact on ALK protein function, signaling pathway activation, tumor proliferation, and invasion." (PMID 40636700, 2025). "Finally, cluster #6 (circulating tumor DNA) highlights the growing interest in liquid biopsy techniques for prognosis prediction and dynamic monitoring of gene mutation status in ALK-positive NSCLC during the last decade." (PMID 40894217, 2025). "In addition, other novel ALK inhibitors, such as ceritinib, brigatinib, and alectinib, while proven to cause tumor shrinkage, inevitably lead to drug resistance or severe adverse reactions." (PMID 40386559, 2025). "Further exploration of using contrast CT for ALK mutation prediction will be considered, as this may provide a more comprehensive tumor assessment and enhance predictive performance." (PMID 40083024, 2025). "Similarly to other neoplasms with plasmablastic differentiation, ALK+ LBCLs express plasma cell-associated markers (CD138, CD38, MUM1/IRF4 and BLIMP1) and are negative or only weakly positive for mature B-cell markers (CD20, CD19, PAX5 and CD79alpha)." (PMID 40869163, 2025). "The only recurrent RTK mutations in NB are ALK mutations, which appear in only 7–10% of NB tumours." (PMID 41511287, 2025). "Additionally, transmission electron microscopy (TEM) analysis of mitochondria in subcutaneous tumors from ALK+ ALCL mouse xenograft models revealed that PTPN2‐deficient tumor cells exhibited an accumulation of swollen and damaged mitochondria." (PMID 40734623, 2025). "Given the response exhibited by our representative case, we surmise that Brigatinib can suppress tumor clones carrying secondary resistance mutations to Ensartinib since Brigatinib could overcome the ALK L1196M mutation in NSCLC." (PMID 38740834, 2024). "The activity of cancer-specific ALK variants is required for tumor maintenance." (PMID 38787978, 2024). "Historically, the association between ALK gene and the tumor has been considered." (PMID 38368344, 2024). "A comparison of the PDC drug sensitivity and clinical tumor response showed that the PDC AUC values for EGFR- or ALK-TKIs were significantly associated with the clinical tumor response (median standardized AUC values: −0.78 in PR, −0.29 in SD, and 0.30 in PD; p < 0.001)." (PMID 38398169, 2024). "It is appropriate to speculate that patients with an ALK-positive stage IB NSCLC tumor smaller than 4 cm and concomitant risk factors such as STAS and VPI could also benefit from adjuvant treatment with alectinib." (PMID 39061248, 2024). "Lorlatinib, a third-generation ALK TKI, has shown encouraging results regarding anti-tumor effects, overcoming intrinsic resistance observed with ALK kinase domain mutations more effectively than first- and second-generation TKIs (e.g., crizotinib and ceritinib)." (PMID 38826727, 2024). "A singleplex test with a short TAT may be beneficial in identifying EGFR or ALK mutations in patients with elevated specific tumor markers." (PMID 38400801, 2024).
tumor (continued). "Although it was unclear whether the IAH1-ALK fusion gene was involved in tumor progression or an asymptomatic mutation, we treated the patient with alectinib, an ALK inhibitor; however, this therapy did not reduce the lesions." (PMID 39781173, 2024). "Interestingly, we detected an IAH1-ALK fusion gene (variant allele frequency 0.39%, tumor fraction 45%), which suggests ALK inhibitors were applicable to his treatment." (PMID 39781173, 2024). "Researchers wanted to know whether the sequencing of circulating tumor cells (CTCs) might provide further insight into ALK drug resistance variants and the possible tumor heterogeneity of ALK-rearranged NSCLC." (PMID 37322261, 2024). "Additionally, ZX-29 effectively hindered mouse tumor growth and showcased its ability to overcome drug resistance stemming from the ALK G1202R mutation." (PMID 38397899, 2024). "Clinical and preclinical studies indicated the efficacy and safety of multiple therapies for NSCLC patients with different aberrations, including EGFR exon 19 deletions or exon 21 (L858R) mutations, RET fusion-positive metastatic, ALK genomic tumor aberrations, EGFR exon 20 insertions." (PMID 37568193, 2023). "In addition, Echinoderm microtubule-associated protein-like 4 (exon 13)-ALK (exon 20) fusion (variant 1) was detected in tumor specimen with a 60-gene panel next-generation sequencing." (PMID 37409244, 2023). "MTOR is associated with the anti-tumor mechanism of ALK inhibitors." (PMID 37906510, 2023). "In the ALK mutation-positive group, there were two clusters with higher tumor frequency." (PMID 37508989, 2023). "In addition, our study also showed that the KRAS mutation-positive group had the largest tumor size (2.83 ± 6.87 cm3) relative to ALK (1.23 ± 3.38 cm3) and EGFR (0.51 ± 2.68 cm3) mutation groups." (PMID 37508989, 2023). "Most BA/CMPT cases have been reported from Japan and other Asian countries and may involve genetic mutations of BRAF, EGFR, KRAS, HRAS, and ALK; thus, the tumor is viewed as an oncological disease." (PMID 39517003, 2023). "Detailed analyses of clonal evolution of two ALK mutations that emerged in an individual tumor revealed F1174L mutations at low allelic fractions in the second and fourth biopsy, and an R1275Q mutation at high allelic fractions from the time of fourth biopsy to the time of final progression." (PMID 36807339, 2023). "According to our limited data, GIST patients with both ALK expression and PDGFRA mutation tend to have a larger tumor diameter, higher recurrence risk and more mitotic figures, indicating that ALK expression may be associated with a worse prognosis." (PMID 37120571, 2023). "Thus, aberrant ALK overexpression is closely associated with tumor development and progression of multiple human malignancies." (PMID 37592266, 2023). "Pairwise comparisons indicated that the mean tumor size for the KRAS mutation-positive group was significantly larger than that of the ALK mutation-positive group (p = 0.01), which was significantly larger than that of the EGFR mutation-positive group (p = 0.001)." (PMID 37508989, 2023). "In two cases, we found two distinct ALK mutations within the same tumor." (PMID 36807339, 2023). "Notably, the upregulation of CSF1 and CCL18—as identified in the TME of ALK-positive tumors —increases type 2 (M2) tumor-associated macrophages (TAM) which have tumorigenic functions and are known to contribute to immune evasion." (PMID 34125345, 2022). "Because of many reasons, such as secondary mutations, tumor heterogeneity, and driving gene conversion, which may cause drug resistance, second- and third-generation ALK-TKIs have been researched and developed." (PMID 35370632, 2022). "Second, there was a lack of complete data collections regarding functional status (e.g., Karnofsky and ECOG performance status scoring) and gene mutation (e.g., EGFR, KRAS and ALK) that may influence tumor progression." (PMID 35388133, 2022).